LCMT2 (leucine carboxyl methyltransferase 2)
Description:
S-adenosyl-L-methionine-dependent methyltransferase that acts as a component of the wybutosine biosynthesis pathway (Probable). Wybutosine is a hyper modified guanosine with a tricyclic base found at the 3'-position adjacent to the anticodon of eukaryotic phenylalanine tRNA (Probable).
Synonyms: KIAA0547; TYW4; MGC9534; PPM2
Tractability: PROTAC: ubiquitination databases record sites on it.
Gene: Protein-coding gene on chromosome 15 (43,323,649 to 43,330,582, reverse strand). Ensembl gene ENSG00000168806.
Subcellular location: Cytoplasm
Subcellular location (Human Protein Atlas): Cytosol
Pathways (Reactome):
Metabolism of RNA: Synthesis of wybutosine at G37 of tRNA(Phe)
Gene Ontology:
Molecular function: protein binding; tRNA methyltransferase activity; methyltransferase activity
Biological process: tRNA methylation; tRNA modification; wybutosine biosynthetic process
Cellular component: cytoplasm
Genetic constraint (gnomAD): Loss-of-function variants: 34 observed, 45.2 expected, observed/expected ratio (o/e) 0.75, 90% interval 0.57 to 1. The upper end of that interval is the gene's LOEUF score, 1, which puts it in group 4 of 6, group 1 being the genes least tolerant of losing a copy. Missense variants: 1,091 observed, 932.22 expected, observed/expected ratio (o/e) 1.17, 90% interval 1.11 to 1.23. Synonymous variants: 445 observed, 385.37 expected, observed/expected ratio (o/e) 1.15, 90% interval 1.07 to 1.25.
Homologues: Orthologues: macaque LCMT2 (95% identical), mouse Lcmt2 (78% identical), rat Lcmt2 (77% identical), guinea pig LCMT2 (76% identical), rabbit LCMT2 (52% identical), zebrafish lcmt2 (44% identical), tropical clawed frog lcmt2 (41% identical). Paralogues in human: LCMT1 (17% identical).
Diseases named in the same sentence as LCMT2 in open-access papers:
LCMT2 is named in the same sentence as 5 diseases in open-access papers, as found by Europe PMC text mining. Sharing a sentence is not in itself a finding about the gene and the disease. The quoted sentences say what the papers report.
Infertility (1 paper, 2023). "Other genes are related to symptoms that are still under investigation, such as neurological sequels (CYB561 and LCMT2) and infertility (RPSAP58 and ASRGL1)." (PMID 36674947, 2023).
renal carcinoma (1 paper, 2025). A carcinoma arising from the epithelium of the renal parenchyma or the renal pelvis. "For example, MARS1 was a significant risk factor in at least 10 cancers, whereas LCMT1 and LCMT2 were protective in several tumors, especially renal cancers." (PMID 41441975, 2025).
cancer (3 papers, 2020 to 2025). A tumor composed of atypical neoplastic, often pleomorphic cells that invade other tissues. "KLHL9, LCMT2, and LZTR1 have been reported to influence cancer progression in different contexts." (PMID 35656299, 2022).
LCMT2 also shares sentences with these, for which no sentence is quoted: breast carcinoma (1 paper); neurodegenerative disease (1).